GADD45B (growth arrest and DNA damage inducible beta)
Diseases named in the same sentence as GADD45B in open-access papers (continued):
Sharing a sentence is not in itself a finding about the gene and the disease.
renal fibrosis (2 papers, 2020 to 2021). A final common manifestation of a wide variety of chronic kidney diseases characterized by glomerulosclerosis and tubulointerstitial fibrosis. "Physiologically, Gadd45β is involved in the regulation of cell proliferation, pro‐inflammatory cytokines and renal fibrosis during the progression of CKD." (PMID 32570293, 2020). "In the current study, we investigated the effects of Gadd45β ablation on cell survival, apoptosis, inflammation and renal fibrosis in mice." (PMID 32570293, 2020). "However, in the present study, we found that Smad7 protein levels in the UUO‐kidney of Gadd45β KO mice were up‐regulated, which subsequently reduce the phosphorylation of Smad2, resulting in less renal fibrosis." (PMID 32570293, 2020). "The current study also showed that Gadd45β regulated TGF‐β1‐mediated Smad signalling in kidney cell lines, suggesting that the Gadd45β‐regulated TGF signalling pathway might be involved in the progression of renal fibrosis." (PMID 32570293, 2020). "Importantly, UUO‐induced renal fibrosis was ameliorated in Gadd45β KO mice unlike in WT mice." (PMID 32570293, 2020).
sarcoidosis (2 papers, 2025). Sarcoidosis is a multisystemic disorder of unknown cause characterized by the formation of immune granulomas in involved organs. "Among the twelve common DEGs, SALL4, WNT10A, RASAL1, CAMK2B were significantly upregulated while GADD45B, KLF4, OLR1, CSF3, WIF1, RAMP3 and AGER downregulated in both sarcoidosis and LC as compared to the controls." (PMID 40797277, 2025). "Additionally, GADD45B functions as a tumor suppressor by mediating DNA damage response, and its significant downregulation in both diseases suggest impaired cellular stress responses, which may contribute to chronic inflammation in sarcoidosis and tumorigenesis in LC." (PMID 40797277, 2025). "While MET is a hallmark of tissue granuloma formation, blood monocytes in both active TU and sarcoidosis exhibited epithelial–mesenchymal transition (EMT) signatures, including significantly increased expression of GADD45B, CD44, CXCL8, ANPEP and THBS1,30, 31, 32, 33 compared with healthy donors." (PMID 40469525, 2025).
steatosis (2 papers, 2021 to 2024). Increased lipid within the cytoplasm of cells. "NAMPT, PHLDA1, RALGDS, GADD45B, and FOSL2 were all in the brown module, with a lower expression for steatosis and NASH samples and with a higher expression for normal samples." (PMID 34041361, 2021). "Unlike the variable expressions of Gadd45β in steatosis, the gene expression changes in HCC are very consistent." (PMID 39653679, 2024).
adenoma (1 paper, 2023). A neoplasm arising from the epithelium. "Five cases of adenoma were observed in Gadd45β WT and only one in Gadd45β KO in the groups with PB treatment." (PMID 37746289, 2023). "However, even though Gadd45β KO mice exhibited lower incidences of adenoma and carcinoma than Gadd45β WT mice in the presence of PB, the same mice showed higher incidences of eosinophilic foci." (PMID 37746289, 2023). "Obtained results showed the disappearance of PB-induced adenoma in Gadd45β null mice." (PMID 37746289, 2023). "The Grubbs test detected the values of liver weight per body weight of two mice, one with carcinoma and the other with adenoma, of PB/DEN treated Gadd45β WT group as outliers." (PMID 37746289, 2023). "In contrast, without PB, Gadd45β WT mice developed no adenoma, whereas Gadd45β KO had two adenomas." (PMID 37746289, 2023).
agranulocytosis (1 paper, 2016). "In addition, carriers of GADD45A rs581000C had a lower risk of anemia, while carriers of GADD45B rs2024144T had a significantly higher risk for leukocytopenia or agranulocytosis." (PMID 26993769, 2016).
AIDS (1 paper, 2019). A syndrome resulting from the acquired deficiency of cellular immunity caused by the human immunodeficiency virus (HIV). "We propose that the coordinated upregulation of CDKN1A, IER3, GADD45B and TNF as well as the positive regulation of calcium-dependent signaling could be involved in the mechanisms leading to the slower progression to AIDS and HIV control concomitantly observed in EC-LTNPs." (PMID 31582776, 2019).
Alzheimer disease (1 paper, 2021). A progressive, neurodegenerative disease characterized by loss of function and death of nerve cells in several areas of the brain leading to loss of cognitive function such as memory and language. "Furthermore, we demonstrate that Gadd45b knockdown results in differential upregulation of genes implicated in neurodegenerative diseases, such as Alzheimer’s disease." (PMID 32927466, 2021).
amoebiasis (1 paper, 2021). "It should be noted that we observed two genes concurrently enriched in three critical pathways: TGFB2 was enriched in the cell cycle, FoxO signaling, and amoebiasis pathways, while GADD45B was enriched in the cell cycle, FoxO signaling, and NF-kappa B signaling pathways." (PMID 33718368, 2021).
atrial fibrillation (1 paper, 2025). A disorder characterized by an electrocardiographic finding of a supraventricular arrhythmia characterized by the replacement of consistent P waves by rapid oscillations or fibrillatory waves that vary in size, shape and timing and are accompanied by an irregular ventricular response. "ECG analysis revealed a high incidence of atrial fibrillation (AF), frequent AF episodes, and prolonged mean AF duration in circNAB1(+) mice following TAC and delivery of EGR1, Gadd45b, or Runx1, comparable to control vector delivered mice." (PMID 40145839, 2025).
autism (1 paper, 2022). Persistent deficits in social interaction and communication and interaction as well as a markedly restricted repertoire of activity and interest as well as repetitive patterns of behavior. "Collectively, these findings suggest that Gadd45b has a vital role in the epigenetic process of autism." (PMID 36311022, 2022). "Furthermore, A microarray analysis has detected elevated Gadd45b expression in the superior temporal gyrus of autism." (PMID 36311022, 2022).
Autoimmunity (1 paper, 2018). The occurrence of an immune reaction against the organism's own cells or tissues. "Two differentially regulated transcripts (TIMD4, GADD45B) would promote inflammation or autoimmunity through involvement of cell death and survival pathways." (PMID 30308012, 2018).
behavioral disorders (1 paper, 2024). "This implies that GADD45β plays a crucial role in the epigenetic processes of complex adolescent social interactions and may offer insights into the etiology of adolescent behavioral disorders." (PMID 38332860, 2024). "Consequently, GADD45β assumes a significant role in the epigenetic programs of complex adolescent social interactions, concurrently offering valuable insights into the etiology of adolescent behavioral disorders such as ADHD, ASD, and/or SCZ." (PMID 38332860, 2024).
Cachexia (1 paper, 2021). Severe weight loss, wasting of muscle, loss of appetite, and general debility related to a chronic disease. "Moreover, in catabolic diseases such as cachexia, GADD45B downregulation occurs and affects muscle tissue regeneration." (PMID 33916982, 2021).
cholangiocarcinoma (1 paper, 2022). A carcinoma that arises from the intrahepatic biliary tree (intrahepatic cholangiocarcinoma) or from the junction, or adjacent to the junction, of the right and left hepatic ducts (hilar cholangiocarcinoma). "The suppression of GADD45B represses cell invasion and migration of cholangiocarcinoma by regulating EMT." (PMID 35699863, 2022).
chondrosarcoma (1 paper, 2010). A malignant cartilaginous matrix-producing mesenchymal neoplasm arising from the bone and soft tissue. "The present study provides the first immunohistochemical evidence that GADD45β expression is significantly associated with the grading of chondrosarcomas." (PMID 20942912, 2010). "In the present study, we investigated the immunohistochemical expression of GADD45β in enchondroma, and chondrosarcoma of histological grades I, II, and III, to clarify the diagnostic significance of GADD45β in pathological grading of chondrosarcoma." (PMID 20942912, 2010). "In the present study, we investigated the immunohistochemical expression of GADD45β in enchondroma and chondrosarcoma of histological grades I, II, and III, to clarify the diagnostic significance of GADD45β in histological grading of chondrosarcoma." (PMID 20942912, 2010). "Therefore, the association of GADD45β expression and pathological grading of chondrosarcoma in the present study suggests that immunohistochemical study of GADD45β may be a specific diagnostic parameter for chondrosarcoma cell differentiation." (PMID 20942912, 2010). "The association of GADD45β expression and pathological grading of chondrosarcoma in the present study suggests that the immunohistochemical study of GADD45β may be a specific diagnostic parameter for chondrosarcoma cell differentiation." (PMID 20942912, 2010). "GADD45β was expressed in 45% (29.8-67.3%) of the cells in grade I chondrosarcoma and 13.8% (1.2-34.1%) of cells in grade II." (PMID 20942912, 2010). "In grade II chondrosarcomas, comparatively mature cells, which had plump nuclei and were surrounded by cartilage matrix, were positive for GADD45β." (PMID 20942912, 2010). "In the case of chondrosarcomas, the percentage of GADD45β positive cells was inversely proportional to the tumor grade." (PMID 20942912, 2010). "On the other hand, the expression of GADD45β decreased significantly according to the histological grade of chondrosarcoma (grade I: 45%; grade II: 13.8%; and grade III: 3.8%)." (PMID 20942912, 2010). "Although we had only 1 case of grade III chondrosarcoma, only 3.8% of the cells were positive for GADD45β." (PMID 20942912, 2010). "Twenty samples (enchondroma = 6, chondrosarcoma grade I = 7, grade II = 6, grade III = 1) were used for immunohistochemical analysis to investigate the expression of GADD45β." (PMID 20942912, 2010).
chronic atrophic gastritis (1 paper, 2023). Atrophic gastritis that is persistent and long-standing. "GADD45B, an oncogene implicated in chronic atrophic gastritis, played a critical role in GC development." (PMID 37608794, 2023). "GADD45B, a cancer-related gene, has been implicated in the development of chronic atrophic gastritis." (PMID 37608794, 2023). "Firstly, the carcinogenic mechanism of GADD45B regulation in chronic atrophic gastritis is a complex process, and this study only provides preliminary evidence." (PMID 37608794, 2023). "Further research can utilize more in vitro and in vivo models, as well as larger-scale clinical samples, to validate the role of GADD45B in carcinogenesis of chronic atrophic gastritis." (PMID 37608794, 2023). "Low levels of GADD45B expression in gastric epithelial cells contribute to the activation of the WNT signaling pathway, thus promoting the carcinogenic process associated with chronic atrophic gastritis." (PMID 37608794, 2023). "Given that chronic atrophic gastritis was an inflammatory disease, we identified GADD45B as a crucial oncogene that might contribute to the development of GC." (PMID 37608794, 2023).
cognitive deficit (1 paper, 2024). "Together, these data suggest that EPO deficiency may be involved in SZ‐related cognitive impairments by activating the GADD45b‐related apoptosis pathway." (PMID 39467064, 2024). "Given the deteriorative effect of GADD45b/p38 MAPK exerts numerous apoptotic events linked to SZ and cognitive impairments, downregulation of GADD45b/p38 MAPK axis may provide a potential strategy for the treatment of SZ‐associated cognitive dysfunction." (PMID 39467064, 2024). "Moreover, overexpression of GADD45b exacerbated neuronal loss and cognitive impairments in male Sprague‐Dawley rats, while downregulation of GADD45b rescued these SZ‐related pathologies." (PMID 39467064, 2024). "Thus, our study not only uncovers a novel role of EPO and GADD45b in the pathological and behavioral abnormalities associated with SZ but also identifies their potential application as therapeutic targets in SZ‐related cognitive deficits." (PMID 39467064, 2024). "A novel etiopathogenic mechanism of SZ‐related cognitive impairments is uncovered, driven by EPO deficiency and the activation of the GADD45b/p38 MAPK axis." (PMID 39467064, 2024). "Taken together, these findings strongly suggest that increased GADD45b is involved in SZ‐related synaptic dysfunction and cognitive impairments." (PMID 39467064, 2024). "In summary, the present study suggests a novel pathogenic link between SZ and cognitive impairments, where EPO deficiency upregulates GADD45b triggering p38 MAPK activation and apoptosis in SZ, thus leading to the synaptic damage and cognitive impairments." (PMID 39467064, 2024). "To investigate whether GADD45b plays an important role in SZ‐related cognitive impairments, we conducted bilateral intra‐hippocampal CA1 injections of either vector or Sh‐GADD45b virus in 8‐week‐old SD rats." (PMID 39467064, 2024). "In addition, supplementation of EPO improved synaptic and cognitive impairments by reducing GADD45b in SZ." (PMID 39467064, 2024). "Moreover, overexpression of GADD45b significantly diminished the protective effects of EPO in MK801‐induced SZ, strongly supporting that the increase in GADD45b is required for EPO deficiency‐related synaptic and cognitive deficit in SZ." (PMID 39467064, 2024).
endometriosis (1 paper, 2022). The growth of functional endometrial tissue in anatomic sites outside the uterine body. "Since endometriosis can be associated with a reduced level of autophagy, GADD45β can participate in the pathogenesis of endometriosis." (PMID 35256739, 2022).
epilepsy (1 paper, 2023). A brain disorder characterized by episodes of abnormally increased neuronal discharge resulting in transient episodes of sensory or motor neurological dysfunction, or psychic dysfunction. "In consideration of species conservation, we jointly analyzed the sequencing results of human peripheral blood samples and mouse tissue samples, and four genes (GADD45B, TMCC3, TPGS2, and KCNJ2) were identified as hub genes in IS and epilepsy." (PMID 37792772, 2023).
esophageal squamous cell carcinoma (1 paper, 2025). Esophageal squamous cell carcinoma (ESCC) is a type of esophageal carcinoma (EC) that can affect any part of the esophagus, but is usually located in the upper or middle third. "The methylation status and protein expression of GADD45G are significantly associated with the survival of esophageal squamous cell carcinoma (ESCC) patients, while the expression of GADD45A and GADD45B is not." (PMID 41018072, 2025).
gastric cardia adenocarcinoma (1 paper, 2017). A carcinoma that arises from glandular epithelial cells of the cardia of stomach. "Furthermore, the study had shown that promoter methylation mediated the repression of Gadd45α and Gadd45β in gastric cardia adenocarcinoma." (PMID 29225771, 2017).
glaucoma (1 paper, 2025). Increased pressure in the eyeball due to obstruction of the outflow of aqueous humor. "Among them, GADD45B, FZD1, EFNA1, LTBP3, and CST3 have been reported to potentially play a role in the development of both AD and glaucoma." (PMID 40988281, 2025).
glioma (1 paper, 2022). A benign or malignant brain and spinal cord tumor that arises from glial cells (astrocytes, oligodendrocytes, ependymal cells). "Hypoxia is also related to the development of gliomas, and both hypoxia and IRE1 inhibition have been shown to promote Gadd45b gene expression in U87 glioma cells." (PMID 36311022, 2022). "In addition, Tricyclodecan-9-yl-xanthogenate also blocks cell cycle progression and inhibits tumor cell growth by decreasing Gadd45b expression in glioma stem cell-like cells." (PMID 36311022, 2022).
Graves disease (1 paper, 2025). Graves' disease is an autoimmune disorder that leads to overactivity of the thyroid gland (hyperthyroidism).It is caused by an abnormal immune system response that causes the thyroid gland to produce too much thyroid hormones. "The levels of GADD45α and GADD45β are lower in psoriatic lesion skin but higher in Grave’s disease, suggesting they may be involved in regulating the pathogenesis of these two diseases." (PMID 40083548, 2025).
Hepatitis (1 paper, 2024). Inflammation of the liver. "Gadd45β is only an accompanying genetic changing during the occurrence of hepatitis, serving as a stress response molecule to alleviate cellular damage caused by inflammation." (PMID 39653679, 2024). "Previous studies have analysed Gadd45β for assessing hepatitis status." (PMID 39653679, 2024). "To date, a definite regulatory effect of Gadd45β on hepatitis has not been determined." (PMID 39653679, 2024).
hyperglycaemia (1 paper, 2024). "The inhibition of liver adipogenesis and inflammation caused by TCPOBOP observed in wild‐type mice was largely eliminated in Gadd45β−/− mice, with CAR activation mitigating hyperglycaemia by hindering glucose production and bolstering hepatic glucose uptake." (PMID 39653679, 2024). "Gadd45β promotes DNA demethylation of PGC‐1α promoter in binding with TET1, thereby stimulating PGC‐1α expression to promote gluconeogenesis and hyperglycaemia." (PMID 39653679, 2024).
inflammatory bowel disease (1 paper, 2020). A spectrum of small and large bowel inflammatory diseases of unknown etiology. "We previously showed that Gadd45β KO mice have delayed wound healing with less proliferation in the intestinal epithelial cells of colon tissues in mice with inflammatory bowel disease." (PMID 32570293, 2020).
ischemia (1 paper, 2016). A hypoperfusion of the BLOOD through an organ or tissue caused by a PATHOLOGIC CONSTRICTION or obstruction of its BLOOD VESSELS, or an absence of BLOOD CIRCULATION. "Moreover, both ischemia and I/H inhibited GADD45β expression (decreased from 6.0±0.4 to 4.6±0.3 in group I, p<0.05; and to 3.6±0.3 in group I/H, p<0.01)." (PMID 27177086, 2016).
lung squamous cell carcinoma (1 paper, 2024). "For example, GADD45B significantly correlates with and may stimulate T‐cell exhaustion in lung squamous cell carcinoma." (PMID 39550701, 2024).
mood disorder (1 paper, 2021). A cognitive disorder a disturbance in which the person's mood is hypothesized to be the main underlying feature. "We quantified mRNA levels corresponding to interneuron marker genes (PV and SST), plasticity genes known to be altered by OTX2 levels (Gadd45b, Arc, Nr4a1), and inflammatory/oxidative stress pathway genes (Mtnd4 and Iba1), given that mood disorders can be related to oxidative stress response." (PMID 33963285, 2021).
Nephropathy (1 paper, 2020). A nonspecific term referring to disease or damage of the kidneys. "A deficiency of Gadd45β led to the lower susceptibility of UUO‐induced nephropathy." (PMID 32570293, 2020).
neuroblastoma (1 paper, 2021). Neuroblastoma (NB) is the most common solid, extracranial childhood tumor. "Since amyloid-like aggregates are frequently cytotoxic, we monitored the effects exerted by exposing human neuroblastoma (SHSY-5Y) and hepatoma (HepG2) cells to GADD45α/GADD45β aggregates and to the three proteins in the native states." (PMID 34639041, 2021).
neurological autoimmune diseases (1 paper, 2022). "Thus, Gadd45b is involved in the regulation of several neurological autoimmune diseases." (PMID 36311022, 2022).
non-Hodgkin lymphoma (1 paper, 2016). Distinct from Hodgkin lymphoma both morphologically and biologically, non-Hodgkin lymphoma (NHL) is characterized by the absence of Reed-Sternberg cells, can occur at any age, and usually presents as a localized or generalized lymphadenopathy associated with fever and weight loss. "In two-hundred and forty-four follicular lymphoma (FL) cases recognized during a population-based case-control study of non-Hodgkin lymphoma (NHL), five genes (GALNT12,BMP7, DUSP2,GADD45B, andADAM17) were found associated with the overall survival of FL and control of B-cell activity." (PMID 27322213, 2016).